ABHD5 (abhydrolase domain containing 5, lysophosphatidic acid acyltransferase)
Diseases named in the same sentence as ABHD5 in open-access papers (continued):
Sharing a sentence is not in itself a finding about the gene and the disease.
colon cancer (8 papers, 2017 to 2024). "Ectopic expression of ABHD5 in TAMs from human and mouse colon cancer tissues activates spermine synthase (SRM) transcription, which in turn inhibits spermidine production." (PMID 37004014, 2023). "ABHD5 promotes autophagy and inhibits tumorigenicity of colon cancer via interacting with and inhibiting the cleavage of Beclin1 by Caspase3." (PMID 34281589, 2021). "Therefore, targeting the ABHD5/SRM/spermine axis of TAMs could be a potential therapeutic strategy for colon cancer." (PMID 37004014, 2023). "This study reveals an unrecognized role of ABHD5 in regulating colon cancer stemness via controlling YAP methylation and nuclear localization, further explaining the molecular mechanism through which ABHD5 functions as a tumour suppressor gene in colon cancer." (PMID 34795238, 2021). "In addition, ABHD5 could also interact with BECN1 to regulate the autophagy and tumorigenesis of colon cancer cells." (PMID 31799599, 2019). "Thus, although ABHD5 established as a tumor suppressor in colon cancer, its regulatory roles in other cancer types have not been investigated." (PMID 29026202, 2017).
neutral lipid storage disease (8 papers, 2007 to 2025). Neutral lipid storage disease (NLSD) refers to a group of diseases characterized by a deficit in the degradation of cytoplasmic triglycerides and their accumulation in cytoplasmic lipid vacuoles in most tissues of the body. "Neutral lipid storage diseases (NLSDs) are genetic disorders caused by mutations in adipose triglyceride lipase (ATGL/PNPLA2) or in α-β hydrolase domain 5 (CGI-58/ABHD5)." (PMID 30795549, 2019).
colorectal tumor (4 papers, 2016 to 2021). "Mechanistically, ABHD5 deficiency promotes colorectal tumor development by inducing glycolysis and epithelial-mesenchymal transition." (PMID 32867817, 2020). "Similarly, in our studies on CRC, we have demonstrated that ABHD5 deficiency promotes colorectal tumour development by inducing glycolysis and epithelial-mesenchymal transition." (PMID 27189574, 2016).
heart failure (4 papers, 2021 to 2024). Inability of the heart to pump blood at an adequate rate to meet tissue metabolic requirements. "It has been verified that cardiac-specific ABHD5 deficiency activates endoplasmic reticulum stress to promote heart failure in mice." (PMID 39726946, 2024). "Our findings suggest that ABHD5-ARID3a have significant potential as predictive biomarkers for heart failure post-AMI which also provides a foundation for further exploration into the molecular mechanisms underlying the progression from AMI to HF." (PMID 39726946, 2024). "Specifically, it was observed that in the peripheral blood of patients who developed heart failure following a myocardial infarction, there was an elevation in the relative CT values, manifesting as an increased expression in ABHD5-ARID3a." (PMID 39726946, 2024). "Previous studies demonstrated that ABHD5 could activate AMPK to further proteolyze HDAC4 into the N-terminal polypeptide of HDAC4 (HDAC4-NT) to protect against heart failure." (PMID 38467717, 2024). "A previous study demonstrated that ABHD5 could further proteolyze HDAC4 into the N-terminal polypeptide of HDAC4 (HDAC4-NT) to protect against heart failure." (PMID 38467717, 2024). "It has also been reported that ABHD5 proteolyzes HDAC4 to maintain cardiometabolic homeostasis during pressure overload and lipotoxicity-induced heart failure." (PMID 39726946, 2024).
endometrial cancer (3 papers, 2021 to 2024). Primary or metastatic malignant neoplasm involving the endometrium (mucous membrane that lines the endometrial cavity). "Shi, from the same research team as Zhou, reported that high ABHD5 expression is associated with poor overall survival (OS) in endometrial cancer patients, as confirmed by univariate and multivariate Cox regression analyses." (PMID 39328203, 2024). "Zhou’s study revealed that ABHD5 is overexpressed in endometrial cancer and is linked to International Federation of Gynecology and Obstetrics (FIGO) stage and lymph node metastasis." (PMID 39328203, 2024). "In our previous research 14, some data implied that ABHD5 might affect endometrial cancer cell invasion via regulating EMT transition." (PMID 35003357, 2021). "ABHD5 may serve as a potential biomarker for endometrial cancer." (PMID 39328203, 2024).
Neutral Lipid Storage Disease with Myopathy (3 papers, 2019 to 2025). "NLSD includes neutral lipid storage disease with myopathy (NLSDM) and neutral lipid storage disorder with ichthyosis caused by mutations in the patatin-like phospholipase domain-containing protein (PNPLA2) and α/β-hydrolase domain-containing protein 5 (ABHD5) genes, respectively." (PMID 40598302, 2025).
idiopathic pulmonary fibrosis (2 papers, 2025). Idiopathic pulmonary fibrosis (IPF) is a nonneoplastic pulmonary disease that is characterized by the formation of scar tissue within the lungs in the absence of any known cause. "ABHD5 may also serve as a potential biomarker, where low ABHD5 expression could potentially accelerate the progression of pulmonary fibrosis." (PMID 40483519, 2025).
liver cancer (2 papers, 2021 to 2024). An epithelial or non-epithelial malignant neoplasm that arises from the liver. "Xu discovered that in hepatocellular carcinoma (HCC) tissues, the expression of ABHD5 is significantly downregulated, and this downregulation is notably correlated with poor prognosis in liver cancer patients, suggesting that ABHD5 is a novel therapeutic target." (PMID 39328203, 2024).
Ataxia (1 paper, 2021). Ataxia refers to impaired coordination of voluntary muscle movement. "This is the case for ABHD5 and ABHD12 causing Chanarin-Dorfmann (OMIM # 275630) and polyneuropathy, hearing loss, ataxia, retinitis pigmentosa, and cataract (PHARC; OMIM # 612674) syndromes, respectively." (PMID 34489854, 2021).
intestinal tumours (1 paper, 2021). "After Abhd5 knockout, intestinal tumours showed a significant increase in the number of Lgr5-GFP-positive cells, characterized as CSCs." (PMID 34795238, 2021). "Similar to the in vitro results, in vivo c-Met expression was higher in intestinal tumours and intestinal mucosa of APCMin/+ mice, with intestine-specific Abhd5 knockout (ApcMin/+/Abhd5f/f/Cre+), than in control mice with intact ABHD5 expression." (PMID 34795238, 2021). "Strikingly, the nuclear translocation of YAP was dramatically increased in an ABHD5 gene dosage-dependent manner in intestinal tumours of ApcMin/+/Abhd5f/+/Cre+ and ApcMin/+/Abhd5f/f/Cre+ mice relative to control (ApcMin/+/Abhd5+/+/Cre+) mice." (PMID 34795238, 2021). "Additionally, the histopathological analysis showed that DPY30 expression levels were substantially higher in intestinal tumours from ApcMin/+/Abhd5f/f/Cre+ mice than in those from control ApcMin/+Abhd5+/+/Cre+ mice." (PMID 34795238, 2021).
keloid (1 paper, 2022). An irregularly shaped, elevated mark on the skin caused by deposits of excessive amounts of collagen during wound healing. "PPARGC1A, PPARG, PLIN1, LPL, ABHD5, lncRNA PART1, lncRNA ENTPD3-AS1 in trunk keloid and DGAT2 in ear keloid showed decreased trend under paired comparation." (PMID 35677827, 2022).
liver dysfunctions (1 paper, 2016). "They shed light on host determinants of HCV and VLDL morphogenesis, on the role of ABHD5 in hepatocytes and the etiology of the liver dysfunctions observed in the Chanarin-Dorfman patients." (PMID 27124600, 2016).
lung adenocarcinoma (1 paper, 2024). A carcinoma that arises from the lung and is characterized by the presence of malignant glandular epithelial cells. "Circ_cMras suppressed lung adenocarcinoma cell progression via the NF-κB pathway by regulating the ABHD5/ATGL axis." (PMID 39328203, 2024). "Zhou’s research highlights the role of ABHD5 in lung adenocarcinoma." (PMID 39328203, 2024). "circ_cMras, ABHD5 and ATGL were expressed at low levels in lung adenocarcinoma cells and tissues." (PMID 39328203, 2024).
non-alcoholic fatty liver disease (1 paper, 2020). "Moreover, monoallelic ABHD5 mutations already predispose to non-alcoholic fatty liver disease." (PMID 32542055, 2020).
prostate tumors (1 paper, 2025). "As a repressor of c-MYC, restoration or pharmacological activation of ABHD5 function may represent a promising strategy for targeting MYC-driven prostate tumors, particularly those with c-MYC overexpression and few actionable mutations." (PMID 41349769, 2025).
sebaceous carcinoma (1 paper, 2024). "Their study examined 27 sebaceous carcinoma cases, 21 basal cell carcinoma cases, and 22 squamous cell carcinoma cases, with extensive immunohistochemical testing validating the diagnostic significance of ABHD5 in sebaceous carcinoma." (PMID 39328203, 2024). "Immunohistochemical analysis revealed high ABHD5 expression in sebaceous tumors, suggesting ABHD5 as a potential diagnostic marker for sebaceous carcinoma." (PMID 39328203, 2024).
tumor (28 papers, 2015 to 2025). "The role of ABHD5, a lipid metabolism regulator, in metabolic reprogramming in tumor-associated macrophages (TAMs) was reported by Shang’s group." (PMID 39328203, 2024). "Previous studies demonstrated that tumor-associated macrophages exhibit heterogeneous expression of ABHD5, with migratory TAMs expressing lower levels of ABHD5 compared to the non-migratory TAMs." (PMID 32867817, 2020). "Importantly, ABHD5 has been implicated in diverse biological functions, including triglyceride mobilization and sequestration, skin barrier formation and tumor suppression, suggesting involvement of metabolic control beyond lipolysis regulation." (PMID 35173175, 2022). "In addition, ABHD5 exhibits low expression in migratory tumor-associated macrophages." (PMID 37671094, 2023). "Hence, deficiency of ABHD5 in colon tissues would be expected to potentiate spermidine production and subsequently suppress tumour growth, seemingly contradicting ABHD5's function as a tumour suppressor." (PMID 27189574, 2016). "Recent studies have identified the lipolytic coactivator α/β-hydrolase domain–containing protein 5 (ABHD5) as a critical regulator of intracellular lipid metabolism and a potential tumor suppressor in several malignancies." (PMID 41349769, 2025). "Beyond its canonical role in lipid catabolism, emerging evidence suggests that ABHD5 contributes to tumor suppression by regulating lipid mobilization, energy stress signaling, and cellular metabolic homeostasis." (PMID 41349769, 2025). "This study paves the way for new treatment possibilities by shedding light on the dual role of ABHD5 in immune regulation—as a tumor-promoting factor and a potential immunotherapeutic target." (PMID 39328203, 2024). "As a key regulator of lipid metabolism, ABHD5 plays a significant role in tumor metabolic reprogramming, particularly in the regulation of lipid metabolism." (PMID 39328203, 2024). "In general, our study demonstrates that FOXC1 exerts its tumor suppressor role by promoting ABHD5 transcription to regulating AMPK/mTOR signal pathway." (PMID 39093497, 2024). "Studies indicate that ABHD5 can exhibit both tumor-suppressive and tumor-promoting effects, underscoring its complex role in the TME." (PMID 39328203, 2024). "In various types of cancer, ABHD5 is abnormally expressed and is involved in the proliferation, invasion, and metastasis of tumor cells." (PMID 39328203, 2024). "This review summarizes the dual roles of ABHD5 in cancer, either as a tumor suppressor or promoter, and explores the potential of ABHD5 as a therapeutic target for cancer." (PMID 39328203, 2024). "Research has also investigated the potential relationship between ABHD5 and tumor immune checkpoint molecules, particularly its interactions with programmed death-ligand 1 (PD-L1)." (PMID 39328203, 2024). "ABHD5, a lipolytic factor either potentiating tumor growth or functioning as a tumor suppressor in certain types of cancer, was significantly downregulated in M2‐like macrophages compared to all other cell types." (PMID 38037545, 2023). "Tumor‐associated marker expression was significantly different among all cell types for MMP2, MMP7, MMP9, MMP12, ABHD5, ADAMTS1, AP‐1, and MGLL each with p < 0.001." (PMID 38037545, 2023). "Together, our structure model and experimental tests provide important new clues to facilitate the understanding of ABHD5 molecular functions in metabolic control, skin barrier formation, Hepatitis C Virus morphogenesis and tumor progression." (PMID 35173175, 2022). "Consistent with the increased number of stem cells, ABHD5-knockdown tumours exhibited more robust growth than control tumours, as indicated by the average final tumour weight." (PMID 34795238, 2021). "Calculation of the stem cell frequency in mouse tumours indicated that ABHD5 knockdown resulted in a 6.8-fold increase in the number of CSCs per tumour compared to that in tumours derived from control cells." (PMID 34795238, 2021).
tumor (continued). "We previously identified a/b-hydrolase domain-containing 5 (ABHD5), an intracellular lipolytic activator that is also known as comparative gene identification 58 (CGI-58), as a novel tumour suppressor in CRC15." (PMID 34795238, 2021). "Recently, multiple lines of evidence suggest that ABHD5 acts as a tumor suppressor because it plays a role in inflammation and lipid metabolism in cancer." (PMID 32867817, 2020). "Recent reports have suggested that ABHD5 was highly expressed in TAMs in the tumor microenvironment." (PMID 32867817, 2020). "Here we report that although ABHD5 plays a tumor suppressor role in CRC development and progression, it unexpectedly blunts the sensitivity of CRC cells to FU via promoting RNASET2-mediated autophagic uracil yield." (PMID 30842415, 2019). "Our previous study established ABHD5 as a tumor suppressor in CRCs, clarifying an important role of ABHD5 function in the cancer field." (PMID 30842415, 2019). "Collectively, these results provide evidence that ABHD5 acts as a metabolic tumor suppressor in PCa that prevents EMT and the Warburg effect, and indicates that ABHD5 is a potential therapeutic target against mCRPC, the deadly aggressive PCa." (PMID 29026202, 2017). "As expected, ABHD5 deficiency-suppressed CRC cell proliferation and tumour growth were rescued by additional C/EBPɛ knockdown in RAW cells." (PMID 27189574, 2016). "In line with the in vitro test results, the xenograft model verified that silence of ABHD5 in RAW cells suppressed CT-26 tumour growth in an SRM-dependent manner." (PMID 27189574, 2016). "We demonstrated that the mRNA levels of ABHD5 were significantly elevated in the tumour tissue-derived macrophages, in contrast to those in the spleen." (PMID 27189574, 2016). "Although PNPLA2 has been recognized as a downstream effector of ABHD5, it remains unclear whether ABHD5 exerts its tumor-suppressive functions exclusively through PNPLA2-mediated lipolysis." (PMID 41349769, 2025). "These opposing conclusions suggest that ABHD5 may influence tumor development through multiple distinct mechanisms." (PMID 39328203, 2024). "Moreover, we and others have demonstrated that ABHD5, the crucial lipolysis activator, actively participates in tumor suppression." (PMID 33219129, 2021). "In this study, we further explored the molecular mechanism responsible for the tumour suppressor function of ABHD5 in CRCs and demonstrated that ABHD5 inhibits YAP-induced c-Met overexpression and CRC stemness through suppressing SET1A-induced YAP and histone methylation." (PMID 34795238, 2021). "Importantly, ABHD5 also functions as a tumor suppressor, and ABHD5 mRNA expression levels correlate with patient survival for several cancers." (PMID 33219129, 2021). "Interestingly, ABHD5 expression was heterogeneous in TAMs and that ABHD5low macrophages (a macrophage subpopulation with decreased expression of ABHD5) potentially facilitate tumor cell migration and cancer metastasis." (PMID 32867817, 2020). "Another mechanism of TAM reprogramming is the triglyceride hydrolysis pathway, where the abhydrolase-domain-containing 5 (ABHD5) in TAMs inhibits the accumulation of reactive oxygen species (ROS), which in turn reduces C/EBPε-dependent spermidine production, and ultimately promotes tumor growth." (PMID 33670011, 2021). "Indeed, tumor progression is accelerated by reduced activity of adipose triglyceride lipase (ATGL, formally PNPLA2), the rate-limiting TG lipase, or loss of αβ hydrolase domain containing 5 (ABHD5), the essential coactivator of ATGL." (PMID 33219129, 2021). "Downregulation of ABHD5 significantly reduces HEC-1A cell growth, tumor volume, and weight in both in vitro and in vivo models." (PMID 39328203, 2024). "In accordance with these findings, DPY30 silencing in ABHD5-knockdown HCT116 cells significantly decreased self-renewal and AI growth in vitro and inhibited xenograft tumour growth and metastasis in vivo." (PMID 34795238, 2021).
tumor (continued). "In our previous study, we have described, a lipolytic factor, ABHD5 (also known as alpha-beta hydrolase domain-containing 5, CGI-58), which functions as an important tumor suppressor in CRCs." (PMID 30842415, 2019). "The CM of ABHD5-overexpressing RAW cells notably stimulated the cell viability, cell cycle, clone formation and tumour growth of CT-26 and MC-38 cells." (PMID 27189574, 2016). "ABHD5 mRNA levels were ubiquitously overexpressed in multiple tissue resident macrophages of TgABHD5 mice compared with wild-type (WT) mice, regardless of tumour inoculation." (PMID 27189574, 2016). "Notably, PNPLA2 knockout failed to phenocopy these effects, indicating that the tumor-suppressive function of ABHD5 is independent of its canonical lipolytic role." (PMID 41349769, 2025). "ABHD5 promotes cell proliferation and invasion by regulating EMT and enhancing the Warburg effect (i.e., aerobic glycolysis enhancement) through the AKT signaling pathway and reduces HEC-1A cell growth, tumor volume, and weight in both in vitro and in vivo models." (PMID 39328203, 2024). "Nevertheless, the mechanisms involved in ABHD5-dependent tumor suppression are not known." (PMID 33219129, 2021). "Similarly, the CM of ABHD5-knockdown RAW cells significantly attenuated the cell viability, cell cycle, clone formation and tumour growth of CT-26 and MC-38 cells." (PMID 27189574, 2016). "EMT is a crucial process in cancer metastasis, and the absence of ABHD5 expression has been demonstrated to increase the invasiveness of HCT116 cells and increase tumor growth in the lungs of a nude mouse model." (PMID 39328203, 2024).